PCSK6 (proprotein convertase subtilisin/kexin type 6)
Description:
Serine endoprotease that processes various proproteins by cleavage at paired basic amino acids, recognizing the RXXX[KR]R consensus motif. Likely functions in the constitutive secretory pathway, with unique restricted distribution in both neuroendocrine and non-neuroendocrine tissues.
Synonyms: SPC4; PACE4
Tractability: Small molecule: a high-quality ligand is known. Antibody: its Gene Ontology location is reachable by antibodies, with high confidence; UniProt places it where antibodies can reach, with medium confidence; UniProt predicts a signal peptide or a membrane-spanning region. PROTAC: ubiquitination databases record sites on it; its protein half-life has been measured; a small molecule that binds it is known.
Target class: Enzyme; Serine protease S8B subfamily; Serine protease SB clan; Protease; Serine protease
Chemical probes: CHEMBL2179834
Gene: Protein-coding gene on chromosome 15 (101,289,784 to 101,525,202, reverse strand). Ensembl gene ENSG00000140479.
Subcellular location: Secreted (Isoform PACE4A-I); Secreted (Isoform PACE4A-II); Endoplasmic reticulum (Isoform PACE4C); Endoplasmic reticulum (Isoform PACE4CS); Endomembrane system (Isoform PACE4E-I); Endomembrane system (Isoform PACE4E-II); Secreted (Isoform PACE4B)
Pathways (Reactome):
Developmental Biology: Formation of the cornified envelope; Signaling by NODAL
Cell-Cell communication: Regulation of CDH1 posttranslational processing and trafficking to plasma membrane
Signal Transduction: NGF processing
Transport of small molecules: Assembly of active LPL and LIPC lipase complexes
Gene Ontology:
Molecular function: endopeptidase activity; heparin binding; nerve growth factor binding; protein binding; serine-type endopeptidase activity; serine-type peptidase activity
Biological process: glycoprotein metabolic process; nerve growth factor production; peptide hormone processing; protein processing; secretion by cell; plasma lipoprotein particle remodeling; regulation of BMP signaling pathway; proteolysis
Cellular component: cell surface; extracellular matrix; extracellular region; Golgi lumen; membrane; plasma membrane; endomembrane system; endoplasmic reticulum; Golgi apparatus
Genetic constraint (gnomAD): Loss-of-function variants: 77 observed, 102.37 expected, observed/expected ratio (o/e) 0.75, 90% interval 0.62 to 0.91. The upper end of that interval is the gene's LOEUF score, 0.91, which puts it in group 3 of 6, group 1 being the genes least tolerant of losing a copy. Missense variants: 1,111 observed, 1,156.5 expected, observed/expected ratio (o/e) 0.96, 90% interval 0.91 to 1.01. Synonymous variants: 476 observed, 458.54 expected, observed/expected ratio (o/e) 1.04, 90% interval 0.96 to 1.12.
Gene-disease validity (ClinGen):
ClinGen rates the evidence that PCSK6 causes each of these diseases.
congenital heart disease (inheritance undetermined): No Known Disease Relationship. A heart disease that is present at birth.
Homologues: Orthologues: macaque PCSK6 (98% identical), chimpanzee PCSK6 (98% identical), pig PCSK6 (93% identical), dog PCSK6 (92% identical), mouse Pcsk6 (91% identical), rat Pcsk6 (91% identical), rabbit PCSK6 (89% identical), guinea pig PCSK6 (83% identical), tropical clawed frog pcsk6 (66% identical), Drosophila melanogaster Fur2 (37% identical), Caenorhabditis elegans kpc-1 (34% identical), zebrafish pcsk6 (32% identical). Paralogues in human: PCSK5 (53% identical), FURIN (37% identical), PCSK4 (34% identical), PCSK1 (32% identical), PCSK2 (29% identical), PCSK7 (28% identical), MBTPS1 (17% identical), TPP2 (14% identical), PCSK9 (11% identical).
Diseases named in the same sentence as PCSK6 in open-access papers:
PCSK6 is named in the same sentence as 81 diseases in open-access papers, as found by Europe PMC text mining. Sharing a sentence is not in itself a finding about the gene and the disease. The quoted sentences say what the papers report.
prostate carcinoma (15 papers, 2015 to 2024). A carcinoma that arises from epithelial cells of the prostate gland. "Previous reports showed elevated ER stress in PCSK6-deficient prostate cancer cells, indicating that PCSK6 has a regulatory effect on ER stress." (PMID 35456517, 2022). "In addition to normal tissues, upregulated PCSK6 expression has been found in many cancers, including lung cancer, breast cancer, prostate cancer, skin cancer, ovarian cancer, and thyroid cancer." (PMID 36362216, 2022). "Similarly, a recent study has shown that limitation of PCSK6 impedes prostate cancer growth in an androgen-independent manner." (PMID 34301174, 2021).
atherosclerosis (8 papers, 2019 to 2024). A disease characterized by the build-up of fatty material and calcium deposition in the arterial wall resulting in partial or complete occlusion of the arterial lumen. "cIMT is a predictive surrogate for atherosclerosis, suggesting that atherosclerotic disease progression is related to the PCSK6 rs1531817 mutation." (PMID 39039525, 2024). "Proprotein convertase subtilisins/kexin 6 (PCSK6) polymorphisms have been shown to be associated with atherosclerosis progression." (PMID 39039525, 2024). "A previous study has shown that PCSK6 polymorphisms are associated with atherosclerosis progression." (PMID 39039525, 2024). "To date, dysregulated PCSK6 expression or function has been implicated in major cardiovascular diseases, including atrial septal defects, hypertension, atherosclerosis, myocardial infarction, and cardiac aging." (PMID 36362216, 2022). "To date, PCSK6 has been implicated in major cardiovascular diseases, such as atrial septal defects, hypertension, atherosclerosis, MI, and cardiac aging." (PMID 36362216, 2022). "A total of 34 candidate causal genes were identified across 14 novel pleiotropic loci and among those, PCSK6 represents possible causal biology with known inhibitors that has large potential to be a therapeutic target for atherosclerosis." (PMID 35186008, 2021). "Some studies suggest that PCSK6 is associated with atherosclerosis." (PMID 39039525, 2024). "PCSK6, as a member of the PCSK family, has polymorphisms that are associated with atherosclerosis progression." (PMID 39039525, 2024). "It was recently discovered in rheumatoid arthritis (RA) and atherosclerosis (AS) that, PCSK6 plays an important role, and high expression of PCSK6 can stimulate the occurrence and progression of inflammatory response." (PMID 37211384, 2023). "Our study also identified specific atherosclerosis-related transcription factors KLF4, KLF11 and BCLAF1 upstream from FURIN, PCSK6 or PCSK7." (PMID 36188622, 2022). "In atherosclerosis, we found that the expression of FURIN, PCSK5 and MBTPS1 was significantly lower in carotid plaques vs. normal artery controls, while PCSK6 and PCSK7 were increased." (PMID 36188622, 2022). "The latest findings suggest that PCSK6-mediated MMP activation may be important in SMC phenotypic changes and pathological vascular remodeling in atherosclerosis." (PMID 36362216, 2022). "Our result supports the idea that the PCSK6/corin/ANP pathway may not play a role in the progression of atherosclerosis." (PMID 31825978, 2019).
breast carcinoma (7 papers, 2016 to 2023). "PCSK6 is a member of the proprotein convertase family that is involved in PCa carcinogenesis and was recently associated with the proliferation, invasion and migration of breast cancer cells by disturbing cell cycle arrest via the mitogen-activated protein kinase pathway." (PMID 34737889, 2021). "In addition, blocking PCSK6 expression in breast cancer MA-MB-231 cells inhibited their proliferation, invasion and migration abilities." (PMID 35281270, 2022). "A previous study revealed that PCSK6 significantly enhanced cell motility, migration, and invasion abilities when they overexpressed in MDA-MB-231 breast cancer cells in vitro." (PMID 35281270, 2022). "For instance, PHTF1, MUC5AC, ZNF192, PCSK6, and HDGFRP3 are shown to be involved in breast cancer, and some common genes such as DCT, ZP2, and CEACAM7 might be involved in breast cancer." (PMID 29589558, 2018).
Hypertension (6 papers, 2015 to 2024). The presence of chronic increased pressure in the systemic arterial system. "PCSK6 variants are associated with hypertension and coronary artery stenosis." (PMID 36362216, 2022). "Reports also indicate 2.34-fold difference in the expression of PCSK6 during maintenance phase of hypertension." (PMID 39268810, 2024).
rheumatoid arthritis (6 papers, 2016 to 2023). A chronic, systemic autoimmune disorder characterized by inflammation in the synovial membranes and articular surfaces. "PCSK6 inhibition reduces inflammatory responses in rat and human synoviocytes associated with rheumatoid arthritis." (PMID 36362216, 2022). "Increased PCSK6 expression has been previously implicated in risk for rheumatoid arthritis." (PMID 27454520, 2016). "With regard to ALI, PCSK6 has been shown to facilitate carotid atherosclerosis and inflammation in rheumatoid arthritis." (PMID 37937296, 2023). "A previous report has suggested that restriction of PCSK6 protects rat models of rheumatoid arthritis against synovitis." (PMID 34301174, 2021). "Importantly, given evidence showing a positive correlation between PCSK6 and inflammation-related genes, inhibiting PCSK6 can provide protection against rheumatoid arthritis, supporting its involvement in inflammatory responses." (PMID 37937296, 2023). "Moreover, increased PCSK6 expression is found in synovial tissues in patients with rheumatoid arthritis." (PMID 36362216, 2022). "Interestingly, knockdown of PCSK6 by RNA interference significantly decreased proliferation, invasion, and migration of cultured rheumatoid arthritis synovial fibroblasts." (PMID 27454520, 2016).
myocardial infarction (5 papers, 2019 to 2023). Gross necrosis of the myocardium, as a result of interruption of the blood supply to the area, as in coronary thrombosis. "Proprotein convertase subtilisin/kexin type 6 (PCSK6) play a key role in cardiac remodeling after acute myocardial infarction." (PMID 36600215, 2023). "The expression of PCSK6 was reported to be elevated in experimental myocardial infarction-induced cardiac remodeling." (PMID 36675993, 2022). "Not only were PCSK6 plaque levels increased in patients with previous myocardial infarction and patients undergoing carotid endarterectomy with stroke symptoms, but the positive correlation observed with MATX components and LRNC volume suggests a possible role of PCSK6 in plaque vulnerability." (PMID 36188622, 2022).
diabetes (4 papers, 2022 to 2024). "Univariate logistic regression revealed that diabetes, previous stroke, heart rate, WBC, ALT, FBG, cTnT, and Fg were risk factors for the high GS, ApoA1/ApoB, and PCSK6 rs1531817 CA + AA genotypes were protective factors against the occurrence of high GS." (PMID 39039525, 2024). "In addition, the PCSK6 gene also activates corin, an important biomarker for salt-sensitive hypertension and diabetes." (PMID 35769078, 2022). "However, these are preliminary findings, and future functional study of the PCSK6 gene in diabetes development are warranted." (PMID 35769078, 2022). "This revealed high IP activity in the field of PCSKs, with patents ranging from biomarkers of diabetes (PCSK1 and PCSK2), to biomarkers and drug targets in cancer (FURIN and PCSK6), with the highest number of patents expectedly related to PCSK9." (PMID 36188622, 2022).
dyslexia (4 papers, 2014 to 2019). A learning disorder characterized by an impairment in processing written words. "The Nodal and Lefty system is cleaved by secreted PCSK6 during the development, and single-nucleotide polymorphisms of PCSK6 have been associated with left handedness and/or dyslexia." (PMID 31825978, 2019). "We recently identified an intronic region of the PCSK6 gene associated with relative hand skill through quantitative GWASs conducted in cohorts of children with dyslexia." (PMID 26908617, 2016). "More direct evidence in support of the dyslexia-specific PCSK6 association comes from very recent functional studies." (PMID 24705331, 2014). "We recently reported the association of the PCSK6 gene with handedness through a quantitative genome-wide association study (GWAS; P < 0.5 × 10−8) for a relative hand skill measure in individuals with dyslexia." (PMID 26908617, 2016). "These interactions could be mediated by concomitant actions in controlling cilia function and could explain the PCSK6 association observed specifically in individuals with dyslexia." (PMID 24705331, 2014). "However, it is curious that the PCSK6 association with PegQ appears to be specific in the dyslexia cohort." (PMID 24275328, 2014). "While PCSK6 was the only gene that reached statistical significance, other genes and pathways involved in the determination of left–right structural asymmetries showed association with handedness both in the cohort selected for dyslexia and in the epidemiological cohort." (PMID 26908617, 2016). "One statistically significant SNP associated with relative hand skill was reported in individuals with dyslexia, which is located in an intron of proprotein convertase subtilisin/kexin type 6 (PCSK6)." (PMID 24275328, 2014).
heart failure (4 papers, 2018 to 2021). Inability of the heart to pump blood at an adequate rate to meet tissue metabolic requirements. "From the 4 predicted proprotein convertases, three PCSK6 PSCK5 and PCSK7, have been previously associated with heart failure, to our knowledge." (PMID 34376786, 2021). "Although the involvement of corin in cardiac hypertrophy and heart failure was extensively studied, to the best of our knowledge this is the first study to examine the alterations in corin and PCSK6 in the pulmonary tissue during CHF." (PMID 29774097, 2018). "Although the involvement of corin in cardiac hypertrophy and heart failure was extensively studied, the alterations in corin and PCSK6, a key enzyme in the conversion of procorin to corin, have not been studied in the pulmonary tissue." (PMID 29774097, 2018).
Stroke (4 papers, 2019 to 2024). Sudden impairment of blood flow to a part of the brain due to occlusion or rupture of an artery to the brain. "South Asia has two unique variants for stroke, rs528002287 and rs148010464, which maps to genes PCSK6 and the intergenic region of PLA2G4A/LINC01036, respectively." (PMID 39268810, 2024). "The risk variants rs528002287 (locus 15q26.3) in PCSK6 and rs148010464 (locus 1q31.1) an intergenic variant in PLA2G4A/LINC01036 for stroke were unique to South Asia, and were found to be associated with cardioembolic stroke and small vessel stroke in South Asians." (PMID 39268810, 2024). "Univariate Cox regression revealed that history of stroke, creatinine (Cr), left ventricular ejection fraction(LVEF), TG, HDL, TC/HDL, ApoB, ApoA1/ApoB, Fg, pulmonary artery pressure (PAP), high GS group, TVD, and PCSK6 rs1531817 genotypes were associated with the occurrence of MACEs." (PMID 39039525, 2024). "Thus, the risk of unique genetic variants in PCSK6 and PLA2G4A in South Asian ancestry may indicate a unique endophenotype for stroke, which might also indicate the influence of underlying risk variants for comorbid conditions, for example PLA2G4A in metabolic processes." (PMID 39268810, 2024).
osteoarthritis (3 papers, 2015 to 2022). A noninflammatory degenerative joint disease occurring chiefly in older persons, characterized by degeneration of the articular cartilage, hypertrophy of bone at the margins and changes in the synovial membrane. "In mice, Pcsk6 deficiency alleviates pain in osteoarthritis models." (PMID 36362216, 2022). "Analysis of Pcsk6 KO mice substantiates a role of PCSK6 in aggrecan degradation and osteoarthritis." (PMID 36362216, 2022).
pancreatic cancer (3 papers, 2021 to 2025). "PCSK6 is upregulated in pancreatic cancer liver metastases, and its inactivation results in the decreased migratory potential of tumour cells in pancreatic cancer and reprogramming of cell‒cell junctions." (PMID 40535770, 2025). "As PCSK6 was up-regulated in pancreatic cancer, inactivation of PCSK6 in both SUIT2 and MIA PaCa-2 was investigated in this study." (PMID 36612240, 2022). "Through GSEA, we found that the high expression of PCSK6 was accompanied by the up-regulation of Kras signaling pathway compared to the group with a relatively low expression of PCSK6, in the cell lines of pancreatic cancer." (PMID 36612240, 2022). "The detailed functions of PCSK6 in tumor cells and its impact on the liver metastasis of pancreatic cancer remain to be determined." (PMID 36612240, 2022). "Through GESA, we noted that the high expression of PCSK6 was correlated with the up-regulation of the Kras signaling pathway compared to the low expression of PCSK6 in the cell lines of pancreatic cancer." (PMID 36612240, 2022). "Using CRISPR/Cas9 technology, we investigated the biological functions and molecular mechanism of PCSK6 involved in pancreatic cancer." (PMID 36612240, 2022). "The results that single clones of both SUIT-2 and MIA PaCa-2 showed lower proliferation rates and fewer colony formation counts compared to controls, indicated that the inactivation of PCSK6 could inhibit the growth of tumor cells in pancreatic cancer." (PMID 36612240, 2022). "PCSK6 was one of the obtained liver-metastasis-related genes in pancreatic cancer." (PMID 36612240, 2022). "In summary, the inactivation of PCSK6 led to the decreased migratory capacity of tumor cells in pancreatic cancer, and reprogramming of cell–cell junctions or the cell skeleton might be one of the causes for this effect." (PMID 36612240, 2022). "Up-regulation of PCSK6 in the liver metastasis of pancreatic cancer was identified in this study." (PMID 36612240, 2022). "PCSK6-targeted therapy might represent a novel approach for combatting liver metastasis in pancreatic cancer." (PMID 36612240, 2022). "Our findings revealed that PCSK6 inactivation could suppress liver metastasis efficiently, and PCSK6 might serve as a novel molecular target for improving the therapeutic efficacy of liver metastasis in pancreatic cancer." (PMID 36612240, 2022). "We demonstrated here that the inactivation of PCSK6 in cell lines of human pancreatic cancer could inhibit cell growth via inducing G0/G1 cell cycle arrest, and could impede cell migration that relied on the remodeling of cell–cell junctions and the cell skeleton." (PMID 36612240, 2022). "Most previous researchers focused on the effect of PCSK6 on cell growth or apoptosis, whereas one study noted that the elevated expression of PCSK6 enhanced the migratory capacity of skin tumor cells, which was consistent with our findings in relation to pancreatic cancer." (PMID 36612240, 2022). "Current evidence has shown that PCSK6 participates in proliferation, migration and apoptosis of tumor cells in different human malignancies, but its role in the liver metastasis of pancreatic cancer remains unclear." (PMID 36612240, 2022). "We have advanced the knowledge by demonstrating that the inactivation of PCSK6 can significantly inhibit the Raf-MEK1/2-ERK1/2 axis, having a repressive effect on cell growth, cell migration and the generation of metastatic niches in the liver in pancreatic cancer." (PMID 36612240, 2022).
preeclampsia (3 papers, 2021 to 2023). Preeclampsia is a hypertensive disorder of pregnancy that is characterized by new-onset hypertension with proteinuria presenting after 20 weeks of gestation, and depending on mild or severe forms may initially present with severe headache, visual disturbances, and hyperreflexia. "More studies are needed to determine if PCSK6 cleaves other substrates in the placenta and if altered PCSK6 expression contributes to gestational hypertension and preeclampsia in humans." (PMID 37569683, 2023).
cardiac hypertrophy (2 papers, 2018 to 2021). "Our findings that PCSK6/corin decreased in decompensated rats but increased in compensated ones may contribute to the enhanced cardiac hypertrophy and decline in Na+ excretion in the former but not the latter." (PMID 34733169, 2021).